FIGNL2 (fidgetin like 2)
Description:
Microtubule-severing enzyme that negatively regulates cell migration and wound healing. In migrating cells, targets dynamic microtubules (MTs) at the leading edge and severs them, thereby suppressing motility. Microtubule severing releases ARHGEF2 which activates RHOA, which in turn regulates focal ahesion turnover via focal adhesion kinase, as opposed to F-actin polymerization, to suppress cell motility. Negative regulator of axon regeneration that suppresses axonal growth by selectively severing dynamic MTs in the distal axon shaft and growth cone (By similarity). Contributes to proper cell branching during endothelial and neuronal development (By similarity).
Tractability: No criterion of Open Targets' tractability assessment is met for any kind of drug.
Gene: Protein-coding gene on chromosome 12 (51,817,899 to 51,848,718, reverse strand). Ensembl gene ENSG00000261308.
Subcellular location: Nucleus; Cytoplasm, cell cortex
Gene Ontology:
Molecular function: ATP hydrolysis activity; microtubule severing ATPase activity; ATP binding
Biological process: microtubule severing; negative regulation of cell migration; morphogenesis of a branching structure; negative regulation of axon regeneration; negative regulation of wound healing, spreading of epidermal cells
Cellular component: cell leading edge; cell cortex; nucleus
Genetic constraint (gnomAD): Loss-of-function variants: 1 observed, 0.84 expected, observed/expected ratio (o/e) 1.19, 90% interval 0.29 to 1.91. That is too few expected variants to judge how well the gene tolerates losing a copy. Missense variants: 943 observed, 645.67 expected, observed/expected ratio (o/e) 1.46, 90% interval 1.38 to 1.54. Synonymous variants: 479 observed, 322.36 expected, observed/expected ratio (o/e) 1.49, 90% interval 1.38 to 1.6.
Homologues: Orthologues: chimpanzee FIGNL2 (99% identical), pig FIGNL2 (93% identical), guinea pig FIGNL2 (86% identical), rat Fignl2 (86% identical), mouse Fignl2 (85% identical), tropical clawed frog gcg.2 (50% identical), Caenorhabditis elegans figl-1 (20% identical), Drosophila melanogaster kat-60L1 (17% identical), Drosophila melanogaster Kat60 (17% identical), Drosophila melanogaster Fign (16% identical), Caenorhabditis elegans mei-1 (15% identical), zebrafish fignl2 (12% identical). Paralogues in human: FIGN (41% identical), FIGNL1 (27% identical), SPAST (22% identical), KATNA1 (18% identical), KATNAL1 (17% identical), KATNAL2 (16% identical), VPS4B (16% identical), VPS4A (15% identical), ATAD1 (14% identical).
Diseases named in the same sentence as FIGNL2 in open-access papers:
FIGNL2 is named in the same sentence as 3 diseases in open-access papers, as found by Europe PMC text mining. Sharing a sentence is not in itself a finding about the gene and the disease. The quoted sentences say what the papers report.
lung carcinoma (1 paper, 2025). "For these genes, FIGNL2 and GFI1 have been studied in lung cancer; FIGNL2 promotes cell growth and tumorigenesis, while GFI1 shows methylation alteration." (PMID 40837413, 2025).
nervous system injuries (1 paper, 2025). "Fidgetin-like 2 (FL2), a microtubule-severing enzyme that negatively regulates axon growth, microglial functions, and wound healing, has emerged as a potential therapeutic target for central nervous system injuries and neuroinflammation." (PMID 40065364, 2025).
tumor (1 paper, 2019). "Differential gene expression analysis revealed 3155 DEGs (differentially expressed genes), among which six AAA ATPase genes (TRIP13, CHTF18, RFC4, ATAD2, FIGNL2, ATAD5) were significantly overexpressed in tumor samples compared to levels in normal samples." (PMID 31533816, 2019).